CYP2R1 (cytochrome P450 family 2 subfamily R member 1)
Diseases named in the same sentence as CYP2R1 in open-access papers (continued):
Sharing a sentence is not in itself a finding about the gene and the disease.
Obesity (continued). "CYP2R1 activity was diminished in an animal model of high fat diet (HFD) obesity, since CYP2R1 mRNA was significantly lower (40%) compared to lean mice, whereas other 25-hydroxylase enzymes were not altered by HFD." (PMID 32911795, 2020). "Further studies are required to clarify if either GR or the PGC‐1α‐ERRα pathway is involved in obesity‐induced repression of CYP2R1 in the kidney." (PMID 33210060, 2020). "• The metabolism of vitamin D to 25OHD by the main 25-hydroxylase CYP2R1 is regulated by metabolic conditions, including obesity." (PMID 32051922, 2020). "Because of ethical reasons, it was not possible to get any liver samples from the patients; therefore, we are unsure if obesity also represses CYP2R1 in the human liver." (PMID 33210060, 2020). "Furthermore, the expression of the vitamin D activator enzyme, CYP2R1, was lower in individuals with obesity." (PMID 40871738, 2025). "Calcifediol could be recommended in patients with obesity, malabsorption syndromes, CYP2R1 dysfunction, or in situations in which a quick, rapid achievement of vitamin D sufficiency is desirable." (PMID 38676447, 2024). "Consequently, epigenetic alterations such as hypermethylation in CYP2R1 and CYP27B1 genes are reported to interfere in the metabolic pathway and decrease vitamin D levels, thereby contributing to genesis of obesity-linked diseases." (PMID 37184736, 2023). "However, similar phenotypes regarding retarded growth, increased obesity, and decreased pgc1α expression have been seen in both cyp2r1-/- and vdra-/-;vdrb-/- zebrafish." (PMID 36864841, 2023). "Another mechanism for decreased 25(OH)D production could be decreased expression of CYP2R1 because animal studies indicated that the expression of many hepatic P450 enzymes (i.e., CYPs) is altered in the context of obesity." (PMID 38179344, 2023). "Our present study clearly indicates that hypermethylation of specific sites in the CYP2R1 and CYP27B1 genes might regulate gene expression with special reference to the risk of obesity and vitamin D metabolism." (PMID 37184736, 2023). "Research has shown that obesity suppresses CYP2R1 expression." (PMID 36532520, 2022). "Obesity represses CYP2R1 expression in human adipose tissue." (PMID 36532520, 2022). "In addition, the expression of cytochrome P450 (CYP2R1), the main vitamin D 25-hydroxylase, has been shown to be decreased in obesity, in both animals, and humans." (PMID 35565910, 2022). "Altogether, these data suggest that the basal Cyp2r1 mRNA expression in the liver decreases with age, and it may be attributed to the development of obesity and lipid accumulation in the liver." (PMID 35524739, 2022). "Vitamin D metabolizing enzyme expression (Cyp2r1, Cyp27a1, and Cyp2j3) was affected by high fat diet-induced obesity, which may partially explain the mechanisms of the modified vitamin D endocrine system related to obesity." (PMID 33195370, 2020). "In summary, we show that obesity affects CYP2R1 expression both in the mouse and human tissues." (PMID 33210060, 2020). "Moreover, obesity repressed the expression of CYP2R1 in several extrahepatic tissues, the kidney, brown adipose tissue, and testis, but not in the white adipose tissue." (PMID 33210060, 2020). "Although CYP2R1 repression in mouse liver is likely to contribute to the obesity‐induced low plasma 25‐OH‐D concentrations, the systemic effect of repression in the extrahepatic tissues currently remains unclear." (PMID 33210060, 2020). "In addition to the liver, CYP2R1 expression was repressed in several extrahepatic tissues in response to obesity." (PMID 33210060, 2020). "In mice, obesity repressed CYP2R1 in the liver, kidney, BAT, and testis." (PMID 33210060, 2020). "Furthermore, we show that in mice, obesity affects CYP2R1 expression not only in liver, but also in several extrahepatic tissues." (PMID 33210060, 2020).
Obesity (continued). "The two SNPs (rs2853564- VDR, rs11023374- CYP2R1) identified in our work have not previously been linked to obesity phenotypes." (PMID 32534577, 2020). "It is currently unclear whether obesity‐induced CYP2R1 repression in adipose tissue could contribute to the reduced plasma 25‐OH‐levels." (PMID 33210060, 2020). "Currently, it is unclear whether the CYP2R1 downregulation in extrahepatic tissues could contribute to the obesity‐induced low plasma 25‐OH‐D, however, this phenomenon may affect at least the local 25‐OH‐D concentrations." (PMID 33210060, 2020). "Furthermore, calcifediol does not require hepatic hydroxylationby the enzyme 25-hydroxylase (CYP2R1), which may have reducedactivity in liver diseases and obesity, as seen in thispatient." (PMID 41123175, 2025). "Patients with class III obesity (BMI > 40) present with low levels of 25(OH)D for various reasons, including nutritional factors, psychological reasons leading to less sun exposure, decreased hepatic expression of CYP2R1, and sequestration of the vitamin in the excess adipose tissue." (PMID 38676447, 2024). "More recently obesity has been shown to decrease hepatic 25-hydroxylase activity causing low 25(OH)D concentrations due to decreased expression of CYP2R1, the principal hepatic vitamin D 25-hydroxylase, while the vitamin D endocrine system is now felt to be far more complex than originally thought." (PMID 36147626, 2022). "This is an important implication that CYP2R1 and CYP27B1 are crucial role players of vitamin D metabolism and pathophysiological mechanisms of obesity." (PMID 37184736, 2023). "Gene-specific hypermethylation in the CYP2R1, CYP27B1, and VDR genes was observed in the obesity-induced mice." (PMID 37184736, 2023). "We previously demonstrated that CYP2R1 expression was suppressed in the mouse liver by fasting, high-fat diet (HFD)-induced obesity and streptozotocin (STZ)-induced diabetes." (PMID 35524739, 2022). "Remarkably, obesity induced by a HFD strongly and significantly repressed the CYP2R1 mRNA expression in the BAT of both male and the female mice by 50% (p = 0.0066) and 65% (p = 0.0008), respectively." (PMID 33210060, 2020). "In obesity and vitamin D metabolism-related gene networks, vitamin D receptor (VDR), cytochrome P450 gene family, i.e., CYP2R1, CYP24A1, and CYP27B1, are key players in vitamin D metabolism and interconnected with energy balance, adipocyte physiology, and adipokine secretion." (PMID 37184736, 2023). "In one study they found that, unlike CYP2R1, there is insufficient evidence that obesity influences VDBP expression in mouse liver, suggesting that these two crucial indicators of vitamin D status are controlled differently." (PMID 36532520, 2022). "The vitamin D synthesis-related genes, DHCR7 and CYP2R1, have not been adequately investigated in relation to obesity and T2D." (PMID 33553043, 2020). "Therefore, liver steatosis does not appear to play a major role in the repression of CYP2R1 as a result of obesity." (PMID 33210060, 2020). "Furthermore, there are no major gender differences in the CYP2R1 response to obesity." (PMID 33210060, 2020). "There is currently no information as to whether obesity affects CYP2R1 expression in humans." (PMID 33210060, 2020).
diabetes (18 papers, 2016 to 2025). "Birth weight showed borderline associations with the diabetes risk–increasing alleles in CYP2R1, rs10741657 (β = −.11, P = .02) and rs12794714 (β = −.09, P = .04)." (PMID 37170809, 2023). "At birth, the diabetes risk–increasing polymorphisms in CYP2R1, which encodes a hepatic microsomal enzyme, were weakly associated with lower weight." (PMID 37170809, 2023). "The diabetes risk–increasing alleles in CYP2R1 (rs10741657 and rs12794714) showed borderline associations with lower birth weight." (PMID 37170809, 2023). "In particular, there is a close linkage between the polymorphism of certain alleles of Cyp2r1 gene, decreased level of circulating 25OHD, and the development of T1D as well as diabetes-associated secondary osteoporosis." (PMID 29552033, 2018). "Other SNPs of the CYP2R1 have been reported to increase the risk of diabetes." (PMID 36364874, 2022). "Since the conversion of vitamin D to 25OHD predominantly catalyzes two cytochrome P450 isoforms (mitochondrial CYP27A1 and microsomal CYP2R1), it was useful to determine whether a significant 25OHD deficiency in diabetes is associated with any changes in the expression of these enzymes." (PMID 29552033, 2018). "This correlated with a study conducted in China to determine the triangular relation between CYP2R1 polymorphisms (rs1993116 and rs10766197), VDD, and type 2 diabetes mellitus." (PMID 41150797, 2025). "According to statistical analysis the allele G and genotype GG of the SNP CYP2R1 rs10741657 and the allele C and CC genotype of the SNP CYP27B1 rs3782130 are associated with a decreased risk of CVDs and diabetes in three of the five heritage models studied." (PMID 40237935, 2025). "The current study was designed, first, to study effect of STZ-induced diabetes in mice on Cyp2r1 expression, vitamin D status, and hepatic vitamin D 25-hydroxylase activity." (PMID 35524739, 2022). "The STZ-induced diabetes significantly repressed Cyp2r1 expression in the liver by 39%, 25%, and 35% after 4, 8, and 13 weeks, respectively, compared to the nondiabetic mice." (PMID 35524739, 2022). "We show that streptozotocin-induced diabetes in mice suppresses the expression of the Cyp2r1 in the liver." (PMID 35524739, 2022). "To analyze the effect of STZ-induced diabetes on vitamin D bioactivation in the liver, we measured the mRNA level of Cyp2r1, the major hepatic vitamin D 25-hydroxylase." (PMID 35524739, 2022). "Nevertheless, the used insulin treatment normalized, either fully or partly, expression of the other diabetes-modified genes studied, indicating that the regulation of Cyp2r1 is rather unusual." (PMID 35524739, 2022). "Considering that age, sex, smoking, drinking, diabetes, and hypertension were confounding factors for CHD, stratification analyses were carried out to estimate the relation between CYP2R1 SNPs and CHD risk." (PMID 34262949, 2021). "Considering that age, sex, smoking, drinking, diabetes, and hypertension were confounding factors for CHD, stratification analysis was also performed to evaluate the contribution of CYP2R1 SNPs to CHD risk." (PMID 34262949, 2021). "The PGC1α/ERRα pathway is physiologically activated during fasting and it is pathologically induced in diabetes: overexpression of this signaling strongly decreased CYP2R1 hydroxylate activity." (PMID 32911795, 2020). "Similarly, diabetes reduces hepatic CYP2R1 mRNA by up to 45%, while fasting decreases it by 80% and total 25‐hydroxylase activity by 50%." (PMID 40831018, 2025). "Additionally, endogenous factors such as OB, starvation, diabetes, and glucocorticoids have a major influence on cytochrome P450 Family 2 subfamily R member 1 (CYP2R1) activity, affecting the production, and in consequence the circulating levels of 25(OH)-D." (PMID 37867510, 2023). "Second, we aimed to study whether insulin therapy could rescue the effect of STZ-induced diabetes on Cyp2r1 expression." (PMID 35524739, 2022).
diabetes (continued). "We observed that the STZ-induced diabetes represses Cyp2r1 expression in the mouse liver." (PMID 35524739, 2022). "However, different from Cyp2r1, the diabetes-induced regulation of Pgc-1α and that of a GR target gene Tat was normalized by insulin treatment." (PMID 35524739, 2022). "Furthermore, the combined effect of CYP2R1 SNPs on CHD patients with diabetes or hypertension was also assessed." (PMID 34262949, 2021). "The initial multivariate logistic regression analysis included the selected SNPs (CYP2R1 rs10741657, CYP27B1 rs4646536, and CYP27B1 rs3782130), adjusted for HBP and diabetes." (PMID 40237935, 2025). "As a result, the final logistic regression model included only CYP2R1 rs10741657 and CYP27B1 rs3782130, adjusted for diabetes." (PMID 40237935, 2025). "Noteworthy, although the basal expression level of Cyp2r1 reduced in the older mice, the relative effect of the STZ-induced diabetes remained very similar." (PMID 35524739, 2022). "In different models of diabetes (HFD induced type 2 diabetes and streptozocin induced type 1 diabetes) a similar suppression of liver CYP2R1 activity was observed." (PMID 32911795, 2020). "Over quartiles of serum 25(OH)D, significant differences were observed for age, sex, BMI, smoking habits, alcohol consumption, physical activity level, season of blood sampling, score of depressive symptoms, self-reported diabetes, DHCR7, and CYP2R1." (PMID 26141257, 2016). "While insulin therapy normalized the blood glucose levels in the diabetic mice, it did not rescue the diabetes-induced suppression of Cyp2r1." (PMID 35524739, 2022). "Similar to the liver, treatment of the STZ mice with insulin or vitamin D did not affect the repressive effect of the STZ-induced diabetes on the Cyp2r1 expression in the kidney." (PMID 35524739, 2022). "Given the known role of T2D itself in lowering vitamin D levels, our present finding clearly indicates that the effect of DHCR7, CYP2R1 and GC variability is independent of hyperglycaemia or other intrinsic features of diabetes status." (PMID 30405883, 2018). "In summary, we demonstrated that Cyp2r1 is repressed by the STZ-induced diabetes in the liver, and the effect could not be corrected by insulin therapy." (PMID 35524739, 2022). "Therefore, the data suggest that neither PGC-1α nor GR plays any major role in the STZ-induced diabetes-mediated Cyp2r1 repression." (PMID 35524739, 2022). "Curiously, insulin therapy did not rescue the diabetes-induced repression of Cyp2r1 in the liver." (PMID 35524739, 2022). "The effects on risk of diabetes were assessed by a genetic score using two 25(OH)D synthesis SNPs (DHCR7-rs12785878 and CYP2R1-rs10741657), with and without the addition of SNPs affecting the transport (GC/DBP-rs2282679) and catabolism (CYP24A1-rs6013897) of 25(OH)D." (PMID 29718904, 2018). "However, CYP2R1 SNPs were not significantly related to diabetes or hypertension in CHD patients." (PMID 34262949, 2021).
rickets (16 papers, 2013 to 2025). Bone softening and weakening usually caused by deficiency or impaired metabolism of vitamin D. Deficiency of calcium, magnesium, or phosphorus may also cause rickets. "This led to evaluation for resistant rickets, which revealed a novel homozygous CYP2R1 c.50_51insTCGGCGGCGC; p.Leu18ArgfsTer79 variant in the affected siblings." (PMID 38440125, 2024). "For example, one study reported on two Saudi adolescent siblings who were diagnosed with short stature and rickets because they had mutations in their CYP2R1 gene." (PMID 36771201, 2023). "Mutations in CYP2R1, the major 25-hydroxylase of vitamin D, that affect CYP2R1 enzyme expression or function have been associated with rickets, low circulating 25(OH)D levels, and decreased sensitivity to vitamin D supplementation." (PMID 35739987, 2022). "It has D-25-hydroxylase activity on both vitamin D, and CYP2R1 deficiency can cause rickets vitamin D-dependent type 1B (VDDR1B)." (PMID 33581688, 2021). "Previous clinical studies on CYP2R1 are limited to only one case report of a Nigerian man with a history of rickets with a point mutation in CYP2R1." (PMID 24073854, 2013). "Haplotype analysis showed that the CAT haplotype of the GC gene (P = 0.005) and the GAA haplotype of the CYP2R1 gene (P = 0.026) were associated with susceptibility to rickets." (PMID 24073854, 2013). "For CYP2R1, individuals with rs2060793 of the G allele were found to confer a significantly increased risk for rickets under the additive and dominant models (P = 0.028 and P = 0.014, respectively)." (PMID 24073854, 2013). "Although polymorphisms within cyp2r1 account for some of the variation in calcidiol concentrations in blood, two missense mutations in cyp2r1 (L99P and K242N) have also been found in Nigerian families having rickets." (PMID 40871701, 2025). "In addition, CYP2R1 variants cause vitamin D related pathologies as rickets as human genetic studies have demonstrated." (PMID 35057442, 2022). "Mutations in CYP2R1 have been found to cause rickets in children from different countries." (PMID 35334824, 2022). "In CYP2R1 knockout mice, circulating 25OHD is reduced by more than 50% and it has been suggested that in some patients with rickets CYP2R1 mutations may be responsible for the disease." (PMID 28912809, 2017). "This study aimed to investigate the association between GC, CYP2R1, and DHCR7/NADSYN1 and rickets in northeastern Han Chinese children." (PMID 24073854, 2013). "This case–control study confirmed the strong effect of GC and CYP2R1 loci on rickets in Han children from northeastern China." (PMID 24073854, 2013). "In this study, the association of GC, CYP2R1, and DHCR7/NADSYN1 polymorphisms with vitamin D deficient rickets in Chinese subjects was reported for the first time." (PMID 24073854, 2013). "In conclusion, our study shows that there are strong effects of GC and CYP2R1 loci on rickets in Han children from northeastern China." (PMID 24073854, 2013). "A mouse model of Cyp2r1 deficiency, however, did not cause rickets although their serum 25OHD was substantially lower than in control mice." (PMID 35334824, 2022).